GFAP (glial fibrillary acidic protein)
Diseases named in the same sentence as GFAP in open-access papers (continued):
Sharing a sentence is not in itself a finding about the gene and the disease.
dementia (229 papers, 2012 to 2026). Loss of intellectual abilities interfering with an individual's social and occupational functions. "The level of p-tau217 was associated with MMSE and FAB scores in dementia-dominant subtype, and the level of GFAP correlated to white matter volume." (PMID 41539185, 2026). "Previous research has indicated that CSF GFAP levels in PD are linked to cognitive decline, though findings about their relationship with dementia conversion has been inconsistent." (PMID 40839564, 2025). "In MCI‐LB, baseline plasma NfL, GFAP, and pTau181 were associated with increased risk of dementia/death and increased cognitive decline measured by the Addenbrooke's Cognitive Examination‐Revised." (PMID 40156325, 2025). "It is possible that the present study was underpowered to find significant associations between CSF GFAP and dementia conversion given the small albeit significant difference in GFAP levels between the groups." (PMID 40839564, 2025). "Higher levels of GFAP and NfL were associated with worse cognitive function and a greater likelihood of dementia in both populations." (PMID 40838581, 2025). "This makes GFAP a promising predictive biomarker for future cognitive decline and dementia associated with AD." (PMID 40690136, 2025). "In contrast, another study, which included a somewhat larger cohort and longer follow up, reported that higher CSF GFAP levels were associated with conversion to dementia." (PMID 40839564, 2025). "Similar to GFAP, blood-based NfL levels in asymptomatic individuals are predictive for subtle cognitive decline and onset of dementia due to AD or other causes." (PMID 40087672, 2025). "This article demonstrates that plasma GFAP, NfL, and pTau181 are associated with the risk of conversion to dementia or death in probable MCI‐LB and are associated with cognitive decline measured using the ACE‐R over a mean of 2.7 years." (PMID 40156325, 2025). "When we evaluated the blood biomarkers individually in our prognostic models, we found specifically that high plasma GFAP, pTau181 and pTau217 were valuable for risk estimation of clinical progression to dementia." (PMID 41339948, 2025). "Advances in ultrasensitive assays now allow reliable quantification of key markers such as p-tau181, p-tau217, NfL, and GFAP in blood, with good predictive performance for neurodegenerative diseases causing dementia." (PMID 40630394, 2025). "In sex-stratified analyses, the associations between the dementia outcomes and p-tau181, p-tau217, and NfL levels were stronger in women, but the association between dementia outcomes and GFAP levels was stronger in men." (PMID 40140622, 2025). "This enhancement was particularly evident when p-tau217 was combined with NfL for all-cause dementia prediction, or with GFAP for AD dementia prediction." (PMID 40140622, 2025). "In a dementia-free Australian community-cohort, plasma pTau-217, NfL and GFAP were associated with cognitive performance and their paired CSF levels." (PMID 41140811, 2025). "The app provides the option to utilise either pTau217 or GFAP alone, or GFAP in combination with pTau181, to determine the risk of progression to dementia and provides 95% confidence intervals for risk estimates." (PMID 41339948, 2025). "Baseline NfL, GFAP, and pTau181 were all associated with an increased hazard of conversion to dementia or death." (PMID 40156325, 2025). "Over recent years, circulating neurofilament light chain and glial fibrillary acidic protein have been independently and jointly associated with dementia risk." (PMID 39175459, 2025). "GFAP levels in both serum and plasma predict dementia onset as well as cognitive decline and grey matter loss in asymptomatic individuals." (PMID 40087672, 2025). "AUCs ranged from 77.5% for GFAP to 82.6% for NfL for all-cause dementia and from 70.9% for NfL to 76.8% for p-tau217 for AD dementia." (PMID 40140622, 2025).
dementia (continued). "Elevation of GFAP (hazard ratio (HR) ranges from 2.25 to 3.15) and NfL (HR ranges from 1.98 to 4.23) increased the risk for several types of dementia." (PMID 38735950, 2024). "Recent large-scale longitudinal studies have shown that elevated GFAP levels are robust prognostic markers for all-cause dementia." (PMID 39297507, 2024). "Elevated baseline expression was correlated with a higher risk of dementia in dementia-free participants, and the NPX values of GFAP and NfL were linked to a genetic predisposition to dementia." (PMID 38735950, 2024). "Another 3-year longitudinal study conducted on 300 CU older individuals found that higher serum GFAP levels at baseline were linked to an increased risk of incident dementia." (PMID 39080712, 2024). "High GFAP levels were also associated with an increased risk of developing other types of dementia (HR = 3.02, 2.21, and 3.05 for ADRD, VD, and FTD, respectively)." (PMID 38735950, 2024). "Consistent with some previous studies, our research confirmed the predictive role of plasma p‐tau181, NfL, and GFAP in future dementia risk." (PMID 38421124, 2024). "When examining subgroups with distinct comorbidities, we observed that elevated GFAP levels heightened the risk of dementia among individuals with organic brain disorders." (PMID 38735950, 2024). "Dementia was associated with higher GFAP (β = 1.54; 95% CI: 1.05–2.0), NfL (β = 0.65; 95% CI: 0.24–1.1) and P-tau181 (β = 0.80; 95% CI: 0.42–1.2)." (PMID 39355007, 2024). "The role of plasma t-tau as a biomarker of dementia risk is less clearly established than those of plasma NfL and GFAP." (PMID 37530894, 2024). "Pro-caspase-6 is observed in astrocytes after transient focal cerebral ischemia in rats, and active caspase-6 is localized together with GFAP in the brain of patients with HIV-associated dementia." (PMID 39001884, 2024). "To overcome these shortcomings, we used a well-documented UK Biobank cohort and evaluated the diagnostic value of peripheral GFAP and NfL levels in a dementia-free population after strict adjustment for multiple confounders." (PMID 38735950, 2024). "In conducting a competing risk analysis, where non-dementia deaths were treated as competing events, we observed a slightly reduced HR for dementia in relation to GFAP, while an increase in HR was noted for NfL." (PMID 38735950, 2024). "The research finding that DMF can inhibit the immunoreactivity of GFAP as well as make astrocytes inactive, indicated GFAP strongly correlated to the progression of postmenopausal-associated dementia." (PMID 38216970, 2024). "We discovered that when combining GFAP and NfL with published models, the predicting values are obviously improved in for all-cause dementia and ADRD." (PMID 38735950, 2024). "In the current study, we investigate if the Okinawa-based Nordic (O-BN) diet alters plasma GFAP levels in patients with Type 2 Diabetes (T2D), a metabolic disorder associated with cognitive disturbances and an increased risk of dementia." (PMID 39275164, 2024). "The non-linear association between plasma GFAP and t-tau and the SVD burden score is in accordance with the non-significant finding of the explained effect by the SVD burden score of the associations between plasma GFAP and t-tau and incident dementia." (PMID 37530894, 2024). "Consistent with previous studies, we found that elevated peripheral GFAP and NfL levels are associated with cognitive impairment and incident dementia and are notably effective in distinguishing participants with dementia." (PMID 38735950, 2024). "Participants with GFAP levels exceeding 0.363 faced a significantly increased hazard of developing all-cause dementia (model 3, hazard ratio (HR) = 2.25; 95% CI = 1.96 to 2.58)." (PMID 38735950, 2024). "Meanwhile, no prospective studies have assessed the association between plasma GFAP levels and risk of dementia." (PMID 38606661, 2024).
dementia (continued). "In summary, our data demonstrated that elevated levels of peripheral GFAP and NfL are associated with cognitive impairment and incident dementia." (PMID 38735950, 2024). "Using GFAP and NfL as the predictors was more effective in predicting all-cause dementia and ADRD compared to using age alone." (PMID 38735950, 2024). "Taken together, higher peripheral GFAP and NfL levels are independent risk factors for cognitive decline and dementia in dementia-free participants." (PMID 38735950, 2024). "Cox proportional hazard models with cross-validations were used to estimate associations between elevated GFAP and NfL with risk of dementia." (PMID 38735950, 2024). "A higher plasma NfL and GFAP were associated with a higher risk of dementia after adjustment for potential confounders (model 2)." (PMID 37530894, 2024). "We therefore used two genetic tools for AD, the AD-GRS and the number of APOE*E4 alleles carrying as independent variables, to explore the association between genetic of dementia and GFAP or NfL." (PMID 38735950, 2024). "Recent studies in CHS have shown that serum NfL and GFAP were associated with substantially higher risk of incident dementia and dementia mortality and WMG worsening over 5 years." (PMID 38765262, 2024). "We extend the results of these previous studies in several ways: we compared and took account of multiple vascular lesions in the brain and examined the contribution of the burden of SVD to the association of plasma NfL, GFAP, and t-tau with incident dementia." (PMID 37530894, 2024). "Cross-sectional studies have reported higher levels of cerebrospinal fluid and blood glial fibrillary acidic protein (GFAP) in individuals with AD-associated dementia than in cognitively unimpaired individuals." (PMID 38439065, 2024). "As such, our findings expand these previous studies by elucidating the value of GFAP for differential risk assessment of all-cause dementia and depression and by adding the information relating to SCC and APOE ε4." (PMID 37951931, 2023). "High GFAP levels are associated with a steeper rate of decline in memory, executive functioning, and attention, and had a high prognostic value for incident dementia in humans." (PMID 37586871, 2023). "The results of the regression models point to the superior diagnostic value of GFAP for dementia as compared to SCC alone and to the other biomarkers of neurodegenerative disease." (PMID 37951931, 2023). "All-cause dementia, AD, and vascular dementia diagnosis, as well as log-transformed levels of NfL, p-tau181, and GFAP in blood." (PMID 36692879, 2023). "Results support the potential role of circulating GFAP levels for aiding dementia risk prediction and improving clinical trial stratification in community settings." (PMID 36056631, 2022). "The association persisted dementia outcomes were assessed at least 2 years after the blood draw for GFAP." (PMID 36056631, 2022). "To reduce the possibility of reverse causation, we repeated the analyses with dementia surveillance beginning at least 2 years after the blood draw for GFAP, finding consistent associations." (PMID 36056631, 2022). "In each of the three cohorts with incident dementia data, higher blood‐derived GFAP levels were associated with increased risk of incident all‐cause and probable AD dementia." (PMID 36056631, 2022). "Results of the meta‐analysis indicated that each one SDU increase in log‐transformed GFAP was associated with an approximate 2.5‐fold higher risk of incident dementia." (PMID 36056631, 2022). "Associations between circulating glial fibrillary acidic protein with cognition, neuroimaging outcomes, and incident dementia stratified by race." (PMID 36056631, 2022). "Higher circulating GFAP concentrations have also been associated with faster cognitive decline and a higher risk of dementia." (PMID 36430485, 2022).
dementia (continued). "After, we performed a deeper analysis of the association of BACE1 with GFAP around vessels in the CA1 area of the hippocampus in human brains with dementia." (PMID 34025357, 2021). "Pro-caspase-6 is observed in astrocytes after transient focal cerebral ischemia in rats and active caspase-6 localizes with GFAP in the brain of patients with HIV-associated dementia." (PMID 31693684, 2019). "In support of this, several studies on CSF- and blood levels of total GFAP in patients of different dementia types, suggest that processes underlying neurodegenerative diseases affect the level of GFAP." (PMID 31693684, 2019). "Among the top 20 proteins in the brain aging clock, those associated with at least two dementia phenotypes included glial fibrillary acidic protein (GFAP), neurofilament light chain polypeptide (NEFL), brevican (BCAN), kallikrein-6 (KLK6) and synaptotagmin-1 (SYT1)." (PMID 41299092, 2026). "The risk charts clearly visualize that an individual with a plasma GFAP concentration in the highest tertile has a much larger 1-, 3- and 5- year risk of progression to any-cause dementia than if the same individual would have had a plasma GFAP concentration in the lowest tertile." (PMID 41339948, 2025). "We hypothesised that higher baseline plasma pTau181, GFAP, and NfL would be associated with a greater hazard of dementia/death and more rapid cognitive decline." (PMID 40156325, 2025). "In addition to VAMP2, we also observed associations of GFAP with synaptic density, yet now within structures typically involved in dementia, such as the precuneus, cingulate gyrus and parahippocampus." (PMID 40620474, 2025). "Notably, the association with PDGFRβ was significantly higher for CSF GFAP levels in the dementia group (β = 0.141 [CI95% 0.055–0.228], P = 0.0020)." (PMID 40239464, 2025). "In addition to being a promising diagnostic biomarker for various neurodegenerative diseases, GFAP can also be utilised for prognostic applications: rate of cognitive decline and higher risk of conversion to dementia." (PMID 39289040, 2025). "Biomarkers linked to dementia neuropathology (e.g., hyperphosphorylated tau, amyloid beta), neuronal injury (e.g., total tau, neurofilament light chain), glial activation (e.g., glial fibrillary acidic protein), and systemic inflammation (e.g., interleukin-6) have shown promise." (PMID 40951922, 2025). "A previous study in nVS PWH with dementia identified elevated levels of TNFα expression in the brain and astrogliosis; however, we did not observe an association between levels of TNFα and the frequency GFAP+ astrocytes in our cohort." (PMID 40469287, 2025). "Elevated preoperative blood NfL and Glial Fibrillary Acidic Protein (GFAP) levels were independently associated with increased risk of postoperative delirium, with NfL and GFAP predicting postoperative delirium even after adjustment for age, sex, dementia, frailty, and IL-6." (PMID 41440533, 2025). "NEFL and GFAP remained significantly associated with incident dementia in the 60-group." (PMID 40061357, 2025). "We also hypothesized that persistent delirium would be associated with both altered dementia biomarkers and also biomarkers of more acute change, namely, GFAP and NfL, and persistent delirium, implicating acute axonal neuronal damage and astrocyte dysfunction." (PMID 39355007, 2024). "The re-evaluation confirmed the robustness of the dementia risks associated with GFAP and NfL." (PMID 38735950, 2024). "Similarly, a stronger association with incident dementia was found for joint NfL and GFAP compared to either of the two individual biomarkers." (PMID 38183363, 2024). "For participants who later manifested dementia, the time to diagnosis was significantly associated with GFAP and NfL levels, but this may be a false positive result due to the large sample size." (PMID 38735950, 2024).
dementia (continued). "Moreover, GFAP has been implicated in various neurological disorders, including dementia, Parkinson’s, and epilepsy, further emphasizing its significance in the context of TBI." (PMID 38735925, 2024). "We also investigated whether associations of NfL, GFAP, and t-tau with incident dementia were explained by SVD." (PMID 37530894, 2024). "Therefore, the diagnostic value of peripheral GFAP and NfL levels should be further explored in dementia-free individuals with larger sample sizes in a population-based cohort." (PMID 38735950, 2024). "Similarly, each unit increase in NfL and GFAP was associated with 8.4% and 1.8% increased risk of dementia progression, respectively." (PMID 38421124, 2024). "Moreover, a significant improvement of the risk assessment ability for incident dementia was observed when adding plasma GFAP or NfL alone to the predicted dementia risk calculated by the risk score consisting of known risk factors for dementia." (PMID 38606661, 2024). "Additionally, plasma GFAP levels, distinguishing dementia risk from depression in non-demented individuals, also demonstrate potential as a marker for early dementia detection." (PMID 38828389, 2024). "Notably, recent large-scale longitudinal studies have reported that elevated plasma GFAP and NfL levels are strongly correlated with an increased risk of all-cause dementia." (PMID 39297507, 2024). "In addition, GFAP has demonstrated predictive value for dementia risk, as higher plasma levels have been linked to increased dementia incidence and mortality in several long-term studies." (PMID 39596011, 2024). "This study additionally showed that the odds of GFAP for all-cause dementia are highly increased by combining high levels of GFAP with persistent SCC and that GFAP is able to predict the risk of all-cause dementia but not of depression in the absence of dementia." (PMID 37951931, 2023). "In addition, we performed survival analyses which showed that the higher the baseline CSF GFAP level in PD–NC patients, the higher the risk of dementia." (PMID 37475029, 2023). "Hence, these additional analyses supported the results showing that in this community-based cohort, high values of GFAP along with persistent SCC were the strongest predictor for dementia risk." (PMID 37951931, 2023). "Furthermore, Cox regression showed that high baseline CSF GFAP levels were associated with a high risk of developing dementia over an 8-year period in the PD–NC group (adjusted HR = 3.070, 95% CI 1.119–8.418, p = 0.029)." (PMID 37475029, 2023). "The unadjusted models exhibited stronger associations between eGFRcr-cys and dementia-related blood biomarkers, with the association with GFAP also reaching significance, but were confounded by age as shown in the age-adjusted models (eTable 6 in Supplement 1)." (PMID 36692879, 2023). "In addition, elevations in baseline GFAP levels were strongly associated with increased risk of incident dementia over the up to 15‐year follow‐up period." (PMID 36056631, 2022). "Furthermore, higher GFAP levels have been associated with an increased risk for future progression to dementia and a steeper cognitive decline." (PMID 36072480, 2022). "Stratified analyses generally indicated similar associations between circulating GFAP with cognition, total and hippocampal brain volume, and incident dementia between Black and White adults; however, the study was underpowered to fully examine race‐specific outcomes." (PMID 36056631, 2022). "Blood levels of GFAP have been associated with cognitive decline and dementia status." (PMID 36056631, 2022). "Additional work has also shown that while high baseline GFAP and NfL were associated with an increased risk of all‐cause dementia, only GFAP remained significantly associated with an increased risk of dementia when both markers were entered together in the same model." (PMID 34859598, 2022).